EGFR (epidermal growth factor receptor)
Diseases named in the same sentence as EGFR in open-access papers (continued):
Sharing a sentence is not in itself a finding about the gene and the disease.
lung adenocarcinoma (continued). "In addition, epidermal growth factor receptor (EGFR) mutations and anaplastic lymphoma kinase (ALK) fusion genes have been identified in lung adenocarcinoma, and are considered as biomarkers for EGFR and ALK inhibitors." (PMID 25348872, 2014). "Our data demonstrates that patients with adenocarcinomas of the lung who are TTF-1 negative have at least a 96% chance of being EGFR wild type when the prevalence of EGFR mutations is approximately 15%." (PMID 25594059, 2014). "TTF-1 protein expression is prevalent in lung adenocarcinomas and is significantly associated with female gender, never-smoking status, presence of EGFR mutations and better overall survival." (PMID 25594059, 2014). "FGFR1 true gene amplification occurred in 17.4% of SCC but was also observed in 3/26 (11.5%) tumors with neuroendocrine differentiation and 2/28 (7.1%) never-smokers with lung adenocarcinoma, including a female with a concurrent EGFR L858R mutation." (PMID 24736592, 2014). "The impact of detection methods on the rates of response to EGFR-TKIs in EGFR-wt lung adenocarcinoma patients is unknown." (PMID 25215536, 2014). "It is well known that mutations of the epidermal growth factor receptor (EGFR) gene are present in some patients with lung adenocarcinoma, with the implication that patients with this genotype were super responders to EGFR-tyrosine kinase inhibitors (TKIs), including gefitinib and erlotinib." (PMID 25527865, 2014). "In conclusion, a significant portion of the erlotinib responses in lung adenocarcinoma patients without detectable EGFR mutations was related to the limitations of detection methods." (PMID 25215536, 2014). "The somatic mutation profile in lung adenocarcinomas lacking targetable EGFR or KRAS mutations or ALK rearrangements in never-smokers is highly complex." (PMID 24576404, 2014). "In addition, HER1/EGFR splicing events have also been identified in lung adenocarcinomas, lending support to our results." (PMID 24428911, 2014). "Univariate analysis of objective response rate of erlotinib treatment in lung adenocarcinoma patients without detectable EGFR mutations at initial molecular testing." (PMID 25215536, 2014). "Activating EGFR mutations are found in about 60% of lung adenocarcinomas in the East Asian population and nonsmoker or former light smoker." (PMID 24836053, 2014). "EGFR-mutant lung adenocarcinoma is nowadays almost considered as a distinct disease entity." (PMID 24739673, 2014). "We identified novel somatic mutations in EGFR/KRAS/ALK-negative lung adenocarcinoma in never-smokers and investigated the mutation frequency of altered genes." (PMID 24576404, 2014). "As EML4-ALK fusion is not as frequent as EGFR gene mutation, it would be important to efficiently and accurately identify those lung adenocarcinomas that harbor ALK rearrangements in clinical practice to guide the appropriate therapy." (PMID 24403104, 2014). "For instance, the EGFR gene, resulted to be DC but not DE, is an important frequently mutated oncogene and a drug target for lung adenocarcinoma." (PMID 24489837, 2014). "Considering the huge amount of data supporting the superiority of anti-EGFR TKIs compared with CT in these patients, every effort should be made to clarify the molecular profile of a lung adenocarcinoma before starting any treatment in everyday clinical practice." (PMID 25300933, 2014). "Besides the mutations in EGFR and KRAS, the targetable translocation EML4-ALK recurrently occurs in lung adenocarcinoma and is most frequent in tumours with mucinous signet-ring appearance." (PMID 24879454, 2014). "For example, EGFR kinase domain mutations are frequent in lung adenocarcinoma of nonsmokers and extremely rare in lung SCC." (PMID 24681604, 2014).
lung adenocarcinoma (continued). "Additional tyrosine kinase inhibitors (TKIs) targeting various cellular signaling pathways have entered the clinic since imatinib mesylate was approved by the FDA in 2001, including inhibitors targeting ERBB2 in breast cancer and the related RTK, EGFR, in lung adenocarcinomas." (PMID 23630663, 2013). "Furthermore, the expression of the EGFR protein was higher in the primary lung adenocarcinoma tissues with -216T/T and -216G/T compared with those with -216G/G (P<0.05)." (PMID 24137392, 2013). "Measuring plasma levels of miR-195 and miR-122 may especially be useful in EGFR mutant patients with lung adenocarcinoma." (PMID 24282590, 2013). "The pathological findings were consistent with TFF1-positive lung adenocarcinoma and no EGFR activating mutations or echinoderm microtubule-associated protein like 4-anaplastic lymphoma kinase (EML4-ALK) translocations were detected." (PMID 24137394, 2013). "The differences between smoking and non-smoking lung adenocarcinoma are found at cellular and molecular levels, including distinct profiles of oncogenic mutations (e.g., EGFR)." (PMID 24282590, 2013). "Therefore, EGFR expression was examined in lung adenocarcinoma patients with various genotypes in order to further clarify the potential molecular mechanism underlying the pleural metastasis associated with the -216G/T variants." (PMID 24137392, 2013). "Currently, there is no published evidence with regard to the frequency of EGFR-activating mutations in patients with lung adenocarcinoma and secondary PC." (PMID 24137394, 2013). "Recent studies of lung adenocarcinoma have suggested that molecular profiling could be of value in future clinical decision making by providing clues about, e.g., treatment response to EGFR inhibitors." (PMID 24205279, 2013). "However, the development of pulmonary fibrosis is a well-known adverse effect of the EGFR inhibitor gefitinib used in the treatment of lung adenocarcinoma." (PMID 23841084, 2013). "In addition, inhibition of miR-21 resulted in increased anti-apoptotic potential of an anti-EGFR tyrosine kinase inhibitor in an EGFR-mutant lung adenocarcinoma cell line." (PMID 23407898, 2013). "Next we sought to determine if DOK2 could inhibit the growth of EGFR-mutant human lung adenocarcinoma cells." (PMID 24255704, 2013). "A high incidence of EGFR gene mutations was reported in female non-smokers with adenocarcinoma of lung: 30–40% in East Asians, as compared with 15% in Caucasians." (PMID 24040073, 2013). "While the lung adenocarcinoma patients with EGFR mutations were predominantly female (64%) and non-smokers (71%), those with wild-type EGFR were predominantly male (77%) and smokers (76%)." (PMID 23879483, 2013). "In this study, we measured the expression of several microRNAs in the plasma of 105 non-smoking female lung adenocarcinoma patients and examined their associations with EGFR mutation and overall survival." (PMID 24282590, 2013). "Moreover, metastasis was diagnosed much less frequently (12 %) in cases of lung adenocarcinoma with wt EGFR." (PMID 23892415, 2013). "Here we show that genomic loss of DOK2 is associated with EGFR mutations in human lung adenocarcinoma, and we hypothesized that loss of DOK2 might therefore cooperate with EGFR mutations to promote lung tumorigenesis." (PMID 24255704, 2013). "In the present study, the -216G/T genotypes of G/T and T/T were detected in patients with pleural metastasis at higher frequencies compared with cases of primary lung adenocarcinoma, and the expression of the EGFR protein was also increased significantly in the former group compared with the latter." (PMID 24137392, 2013). "Epidermal growth factor receptor (EGFR) mutations are common in lung adenocarcinomas of never smokers, while KRAS mutations are more frequent among heavy smokers." (PMID 24179496, 2013).
lung adenocarcinoma (continued). "Moreover, ionizing irradiation of human lung adenocarcinoma cells increased SGLT1 expression as a survival mechanism that depends on EGFR signaling." (PMID 23637683, 2013). "Therefore, a stepwise approach to test for gene mutations in lung adenocarcinoma is suggested: first for KRAS, second for EGFR, and then EML4-ALK translocation." (PMID 23341890, 2013). "Our results indicated that high expression of miR-19a, miR-19b, miR-195, miR-122 and miR-590-5p in plasma were associated with better overall survival among non-smoking female lung adenocarcinoma patients who had EGFR mutation." (PMID 24282590, 2013). "Furthermore, our IHC staining demonstrated that increased expression of Nanog and nuclear translocation of β-catenin occurred concomitantly in response to EGFR signaling in A549 and H23 lung adenocarcinoma cells." (PMID 23648139, 2013). "The patients with advanced lung adenocarcinoma might get benefits from pemetrexed-based or platinum-based chemotherapy after they were EGFR-TKIs resistace." (PMID 24113006, 2013). "One important question is that why the skin rash emerged on the normal skin of the patients of lung adenocarcinoma with EGFR mutation, although did not without EGFR mutation." (PMID 23420789, 2013). "Furthermore, in adenocarcinomas of the lung which have been treated with novel EGFR tyrosine kinase inhibitors, conversion to a small cell phenotype and EMT has been identified as one of several resistance mechanisms to evade therapy." (PMID 23536778, 2013). "We profiled miRNAs extracted from the plasma of different EGFR mutation status lung adenocarcinoma patients (non-smoking female) using TLDA." (PMID 24282590, 2013). "Patients with these pathological features of lung adenocarcinoma may benefit from EGFR-TKI as postoperative chemotherapy or first-line chemotherapy of relapsed lung adenocarcinoma." (PMID 22225786, 2012). "In order to investigate this hypothesis, we downregulated EGFR in NCI-H1975 lung adenocarcinoma cells that have activated EGFR, using small interfering RNA, and analyzed RBM5 expression [CMJ, submitted]." (PMID 22537942, 2012). "In lung adenocarcinoma, activating mutations in the gene encoding epidermal growth factor receptor (EGFR) are frequent in tumors of never smokers of Asian origin, predicting therapeutic sensitivity to Egfr-targeting drugs." (PMID 23244191, 2012). "Good examples are epidermal growth factor receptor (EGFR) mutation for predicting the effectiveness of EGFR tyrosine kinase inhibitors (TKIs) in lung adenocarcinoma, as well as KRAS mutation for predicting the unresponsiveness of EGFR monoclonal antibody in colorectal cancer (CRC)." (PMID 23209813, 2012). "The lipid metabolism pathway may also modulate the effectiveness of EGFR-TKIs in lung adenocarcinoma patients." (PMID 22211244, 2012). "In our previous study, approximately 90% of lung adenocarcinomas from never smokers harbor known oncogenic mutations in just 4 genes of EGFR, KRAS, HER2, EML4-ALK." (PMID 22140546, 2011). "Better treatment outcomes of EGFR-TKIs were shown in females, non-smokers, and patients with lung adenocarcinoma, and thus it is not surprising to observe frequent amplifications (52%) and mutations (83%) of EGFR in our results." (PMID 21935476, 2011). "Mutations in the EGFR kinase domain predict sensitivity to the tyrosine kinase inhibitors gefitinib and erlotinib in lung adenocarcinoma, while activating point mutations in KRAS and BRAF confer resistance to the anti-EGFR monoclonal antibody cetuximab in colorectal cancer." (PMID 21943394, 2011). "However, the mutations in either gene in lung adenocarcinomas are rarely seen although the biological consequences of KRAS and EGFR mutations share similarities in regulation of cell proliferation, survival and apoptosis." (PMID 22174919, 2011).
lung adenocarcinoma (continued). "Sixty-one (45.8%) of the 133 cases showed EGFR expression levels corresponding to 3+, 30 (22.6%) cases showed EGFR levels of 2+, and 23 (17.3%) cases showed EGFR levels of 1+; the remaining 19 (14.3%) cases showed level 0 staining (n = 133 lung adenocarcinoma samples)." (PMID 20637128, 2010). "Our approach is tested on gene expression data on i) acute lymphocytic leukemia (ALL) with and without BCR/ABL gene rearrangement and ii) lung adenocarcinoma with and without EGFR mutation." (PMID 20809931, 2010). "We also identified 105 EGFR CNG in same subset of 269 lung adenocarcinomas." (PMID 19826477, 2009). "Lung adenocarcinomas, in which the expression of EGFR has noprognostic value, may also be treated with gefitinib or erlotinib." (PMID 18769552, 2008). "Thus, these experiments showed that persistent EGFR signalling is required for tumour maintenance in human lung adenocarcinomas expressing EGFR mutants." (PMID 17325698, 2007). "Mutations observed in EGFR, KRAS, BRAF, and FGFR4 in lung adenocarcinomas." (PMID 17487277, 2007). "Furthermore, the DLDA predictive models suggest improved prediction of EGFR TKI sensitivity of human lung adenocarcinomas compared to single biomarkers alone." (PMID 17096850, 2006). "The growth stimulus that ligand-activated erbB-2 and EGFR provides to lung adenocarcinoma cells may establish a background of continued cell proliferation over which other critical transforming events may occur." (PMID 7599067, 1995). "Additionally, to the rare occurrence of de novo small-cell lung cancers (SCLCs) in non-smokers (<2%), some SCLCs are believed to develop through the transformation of lung adenocarcinomas (LUADs), a type of non-small-cell lung cancer (NSCLC) that carries EGFR mutations or ALK alterations (~14%)." (PMID 39858036, 2025). "Therefore, in this study, we aimed to analyze the treatment efficacies and toxicities of combination therapy in patients with advanced EGFR-mutant lung adenocarcinoma (LUAD) with MET overexpression after progression from EGFR TKI treatment in the real-world setting." (PMID 40470164, 2025). "For lung adenocarcinoma, the GPA score incorporates key prognostic factors, including KPS, age, presence of extracranial metastases (ECM), number of brain metastases, and the molecular status of epidermal growth factor receptor (EGFR) mutation and ALK gene fusion." (PMID 41296115, 2025). "While our study provides evidence using LUAD cells harboring KRAS or EGFR mutations and KRASG12D-driven lung adenocarcinoma, it would be valuable to investigate whether this mechanism occurs in other cancers with different oncogenic changes that consistently activate ERK." (PMID 40860160, 2025). "We present a rare case of dermal lymphatic carcinomatosis arising from epidermal growth factor receptor (EGFR)-positive lung adenocarcinoma, a presentation that may closely mimic inflammatory dermatoses and indicate therapeutic resistance or disease progression." (PMID 41542005, 2025). "However, in three patients with lung adenocarcinoma harboring an activating EGFR kinase mutation (EGFR p.E746_A750del, p.S768I, and p.L858R) without previous EGFR-targeted therapies, we detected seven, four, and three actionable alterations, respectively." (PMID 39847581, 2025). "Lung adenocarcinoma (LUAD) demonstrated a contrasting pattern, where elevated HuR linked to reduced WEE1 inhibitor (MK-1775) efficacy (R = -0.28, p < 0.01) but enhanced sensitivity to platinum agents (Cisplatin) and wild-type EGFR-TKIs (Erlotinib; R = 0.35-0.42, p < 0.01)." (PMID 40853971, 2025). "Therefore, we provide data on trends in OS of unselected patients with stage IV lung adenocarcinoma and EGFR or KRAS mutation, or no-mutation in a current and historic real-world population." (PMID 40227775, 2025). "However, to the best of our knowledge, no studies have demonstrated that MCAM may regulate the resistance of lung adenocarcinoma to EGFR-TKIs through the JAK3 signaling pathway." (PMID 40713600, 2025).
lung adenocarcinoma (continued). "Approximately 40% of Asian lung adenocarcinoma (LUAD) patients have driver gene mutations and could benefit from targeted therapies, such as tyrosine kinase inhibitors (TKIs) targeting sensitizing mutations in the epidermal growth factor receptor (EGFR)." (PMID 39773749, 2025). "Additionally, CAFs exhibit primary resistance to EGFR-TKIs in EGFR-mutant lung adenocarcinoma." (PMID 40003951, 2025). "Additionally, it was recently suggested that HPV 16E6/18E6 oncoproteins and epidermal growth factor receptor (EGFR) expression may serve as good prognostic factors in patients with lung adenocarcinoma." (PMID 39409943, 2024). "Furthermore, si-circPRKCI can enhance the inhibitory effect of epidermal growth factor receptor (EGFR)–tyrosine kinase inhibitors in HCC827 cells, which may enhance the therapeutic effect of these inhibitors in lung adenocarcinoma with EGFR mutations." (PMID 38741779, 2024). "A phase 3 open-label study (IPASS) found gefitinib to be more effective than carboplatin plus paclitaxel for initially treating lung adenocarcinoma in East Asian non-smokers or former mild smokers, suggesting that patients with EGFR mutations benefit most from gefitinib as a first-line treatment." (PMID 39872524, 2024). "Therefore, our research focuses on patients with EGFR/ALK wild‐type lung adenocarcinoma who may benefit from ICI treatment." (PMID 38396367, 2024). "The prevalence of epidermal growth factor receptor (EGFR) mutations in Asian populations, including Vietnam, ranges from 39.6 to 51.4%, while specifically in Vietnam, the reported rate of EGFR gene mutations in patients with adenocarcinoma of the lung ranges from 40.7–64.2%." (PMID 38317094, 2024). "In lung adenocarcinoma, EGFR was linked to increased migration, but not EMT." (PMID 36550787, 2024). "Indeed, our results showed that PD-L1 positive cases have worse RFS than PD-L1 negative cases in EGFR-mutated lung adenocarcinoma, but not in EGFR-wildtype lung adenocarcinoma." (PMID 39281386, 2024). "Importantly, this study suggests that the expression of HPV 16E6/18E6 and EGFR may serve as a predictive biomarker of survival in patients with lung adenocarcinoma." (PMID 39409943, 2024). "EGFR mutation has been found to induce synthetic lethality with KRAS mutation in lung adenocarcinoma, which could explain why both mutations do not usually coexist in pancreatic cancer." (PMID 38607041, 2024). "However, despite the remarkable prognostic benefits offered by osimertinib, a population of patients with EGFR-mutated lung adenocarcinoma who are at high risk for postoperative recurrence has not yet been clearly identified." (PMID 39281386, 2024). "We obtained surgical tissue samples of known EGFR-driven lung adenocarcinoma cases from the Mayo Clinic Thoracic Specimen Registry33 (NCT04118660); an aliquot of each sample was flash-frozen at the time of resection, and another aliquot was cryopreserved for subsequent culture." (PMID 38538642, 2024). "Moreover, JAK inhibition has been proposed to counteract drug resistance mechanisms; for instance, targeting JAK2 in EGFR-mutant lung adenocarcinoma can restore the effectiveness of EGFR inhibitors like erlotinib and gefitinib by modulating interactions with SOCS5." (PMID 39682234, 2024). "Therefore, the clinical significance of adjuvant EGFR‐TKIs in stage IB lung adenocarcinoma may be underestimated." (PMID 37559419, 2023). "Furthermore, various cancer treatments can induce resistance in parallel with the conversion of the epithelial tumor to a neuroendocrine variant: anti-androgens induce such an alteration in prostate cancer, while EGFR inhibitors induce similar conversion in lung adenocarcinomas." (PMID 36754910, 2023). "In addition, EGFR-KRAS signaling in lung adenocarcinoma suppresses MTSS1 and upregulates PD-L1." (PMID 36810288, 2023).